PLEC (plectin)
Diseases named in the same sentence as PLEC in open-access papers (continued):
Sharing a sentence is not in itself a finding about the gene and the disease.
liver cancer (4 papers, 2018 to 2025). An epithelial or non-epithelial malignant neoplasm that arises from the liver. "However, a recent study showed a low expression of plectin in liver cancer cells, accompanied by a high cell migration rate, suggesting an inhibitory effect of plectin on liver cancer cell migration." (PMID 29587367, 2018). "Plectin may serve as a potential phosphobiomarker in liver cancer." (PMID 41169522, 2025).
lung adenocarcinoma (4 papers, 2011 to 2024). A carcinoma that arises from the lung and is characterized by the presence of malignant glandular epithelial cells. "In addition to the studies of plectin functions in lung CSCs, we analyzed the expression of plectin in clinical studies and found the high expression of plectin is associated with poor survival of lung adenocarcinoma patients." (PMID 31628412, 2019). "CSP’s functional significance has revealed high plectin expression as an indicator for poor prognosis in CSP+ cancers such as lung adenocarcinoma and head and neck squamous cell carcinoma." (PMID 34571866, 2021). "Our studies show both genotypic and phenotypic correlations between plectin and lung CSCs, as well as association of high plectin mRNA expression with poor patient survival in lung adenocarcinoma, potentially identifying plectin as a biomarker for lung CSCs." (PMID 31628412, 2019). "In this regard, higher tumor plectin mRNA expression is strongly associated with poor overall survival in lung adenocarcinoma and in non-smoking patient but not in lung squamous cancer." (PMID 31628412, 2019).
squamous cell carcinoma (4 papers, 2016 to 2024). A carcinoma arising from squamous epithelial cells. "As an opposing observation, the high plectin expression level is associated with better survival in squamous carcinoma patients although the difference is very small (HR = 0.75, P = 0.044)." (PMID 31628412, 2019). "A cross talk has been proposed for hemidesmosomal integrins α6β4 and focal contact-localized integrins α3β1 in epidermal keratinocytes and squamous cell carcinomas involving CD151 and plectin with complex consequences for cell migration." (PMID 27007410, 2016).
astrocytomas (3 papers, 2017 to 2024). "Similarly enigmatic to plectin–nestin interactions in astrocytes are interactions of plectin with synemin, which is expressed in astrocytomas as well as immature and reactive astrocytes, where it incorporates into vimentin filaments and associates with GFAP." (PMID 34572001, 2021). "Focal adhesion formation is essential for cell migration and invasion and our previous studies indicated that changes in the expression of GFAP-isoforms regulate expression of plectin and integrins, genes involved in focal adhesion formation and the size of focal adhesions in astrocytoma cell lines." (PMID 29152145, 2017). "For validating plectin’s potential as a biomarker of GBMs, it will be essential to investigate its re-localization within the cytoplasm, assess its surface expression, and measure the direct release of plectin in biopsy specimens obtained from GBMs and lower-grade astrocytomas." (PMID 38263015, 2024). "Surprisingly, in the case of astrocytoma, the biomarker potential of plectin has not been thoroughly addressed yet." (PMID 34572001, 2021).
bladder cancer (3 papers, 2018 to 2024). "In bladder cancer, plectin is closely associated with the formation of invadopodia and the cancer cell invasion." (PMID 39334817, 2024). "Plectin was found to be upregulated in a high-metastatic subpopulation of the bladder cancer cell line, KK-47." (PMID 34571895, 2021). "In vivo, tail-vein injection of plectin knockdown bladder cancer cells resulted in a significant reduction of metastases compared to the administration of cancer cells with rescued plectin and endogenous plectin expression." (PMID 34571895, 2021). "Afterward, in invasive bladder cancer cells, plectin forms a complex with vimentin IFs and F-actin at the base of invadopodia." (PMID 34571895, 2021). "Western blot analysis revealed increased plectin expression in additional invasive bladder cancer cell lines, T24, BOY, and YTS-1, compared to non-invasive bladder cells, RT4 and 5637." (PMID 34571895, 2021). "Moreover, in high-metastatic bladder cancer, plectin plays a key role in anchoring invadopodia to IF and in stabilizing invadopodia, which is critical for cancer cell invasion." (PMID 29587367, 2018).
congenital muscular dystrophy (3 papers, 2016 to 2023). A muscular dystrophy that is characterized by diminished muscle tone (hypotonia), progressive muscle weakness and degeneration (atrophy), abnormally fixed joints, spinal rigidity, and delays in reaching motor milestones such as sitting or standing unassisted. "Abnormalities in the PLEC gene are known to be one of the key factors causing congenital muscular dystrophy and malnutrition, and we have identified a significant number of genetic variations in the PLEC gene." (PMID 38067002, 2023).
esophageal squamous cell carcinoma (3 papers, 2020 to 2025). Esophageal squamous cell carcinoma (ESCC) is a type of esophageal carcinoma (EC) that can affect any part of the esophagus, but is usually located in the upper or middle third. "Additionally, some studies have indicated that PLEC may be a novel susceptibility gene in testicular cancer and esophageal squamous cell carcinoma." (PMID 33091877, 2020). "A quantitative proteomic analysis of esophageal squamous cell carcinoma (ESCC) tissue identified plectin as overexpressed in malignant tissue compared to adjacent normal epithelium." (PMID 34571895, 2021). "In esophageal squamous cell carcinoma (ESCC), plectin is frequently overexpressed." (PMID 41011568, 2025).
glioblastoma (3 papers, 2022 to 2025). The most malignant astrocytic tumor (WHO grade IV). "In the present study, we demonstrate that the expression and localization of plectin in brain tumors correlate with those of AQP4 and that the abundance of plectin on the extracellular leaflet of the plasmalemma is increased in glioblastoma cells." (PMID 38263015, 2024). "The expression of aquaporin 4 (AQP4) and intermediate filament (IF) proteins is altered in malignant glioblastoma (GBM), yet the expression of the major IF-based cytolinker, plectin (PLEC), and its contribution to GBM migration and invasiveness, are unknown." (PMID 38263015, 2024). "mTORC2-associated interactome showed actin-binding proteins and microtubule-associated proteins significantly changed depending on mTORC2 activity level in glioblastoma, including Myosin-9/MYH9, Plectin/PLEC and MAP1B." (PMID 36552831, 2022).
glioma (3 papers, 2011 to 2021). A benign or malignant brain and spinal cord tumor that arises from glial cells (astrocytes, oligodendrocytes, ependymal cells). "Although the first proof that plectin interacts with microtubules was obtained by experiments performed on glioma C6 cell extracts, and soon after in brain microtubule preparations, the extent of plectin associations with microtubules in astrocytes remain to be investigated." (PMID 34572001, 2021). "C6 glioma cells were also instrumental in demonstrating the interaction between plectin and actin; i.e., immunogold labelling in C6 glioma cells was used to demonstrate that plectin molecules link IFs among themselves and with actin filaments." (PMID 34572001, 2021). "At the time of the discovery, when it was isolated as a high molecular weight polypeptide in rat glioma cell lysates, plectin was proposed to serve as a linker component between microtubules and intermediate filaments (IFs)." (PMID 34572001, 2021). "In glial cells, the interaction between plectin and IFs was first observed in rat glioma C6 cells, where the distribution of plectin was detected along vimentin filaments, and extensive crosslinking between plectin and reconstituted vimentin filaments was corroborated in vitro." (PMID 34572001, 2021). "Among a series of different conditions tested, including those leading to polymer formation of recombinant RDs, solubilization of glioma C6 cell plectin in low ionic strength buffer in the presence of 10 mM CaCl2 was found to be favorable for oligomerization of plectin." (PMID 22144912, 2011).
head and neck carcinoma (3 papers, 2017 to 2024). A carcinoma that arises from the head and neck region. "Emerging evidence has revealed that plectin overexpression is also characteristic of several head and neck cancers." (PMID 34571895, 2021). "In particular, plectin’s cancer-specific cell surface mislocalization has revealed plectin expression as a biomarker or prognostic indicator in several cancers, including pancreatic, ovarian, lung, prostate, and head and neck cancer." (PMID 34571895, 2021). "Two studies evaluated plectin as a prognostic marker in head and neck carcinomas, however, they presented results opposed to ours." (PMID 29088820, 2017). "Plectin demonstrates increased expression in tumor tissue compared to normal tissue across multiple cancers, including pancreatic, ovarian, prostate, lung, and head and neck carcinoma, among others." (PMID 34571895, 2021).
neuropathies (3 papers, 2021 to 2025). "Mutations in the PLEC gene or plectin deficiencies have been linked to a spectrum of human diseases, characterized by muscle weakness and atrophy, skin fragility and blistering, as well as signs of neuropathy." (PMID 41011568, 2025). "Thus, regarding undiagnosed neuropathies and neurological disorders, additional, and potentially isoform P1c‐specific, plectin mutations can be expected to be identified in the near future." (PMID 32484610, 2021). "Revealing a regulatory role of plectin scaffolds in microtubule‐dependent nerve cell functions, our results have potential implications for cytoskeleton‐related neuropathies." (PMID 32484610, 2021).
osteoarthritis (3 papers, 2020 to 2025). A noninflammatory degenerative joint disease occurring chiefly in older persons, characterized by degeneration of the articular cartilage, hypertrophy of bone at the margins and changes in the synovial membrane. "The osteoarthritis risk-conferring allele rs11780978 (G > A), located upstream of the exon P1c coding region, correlated with reduced plectin expression due to methylation at a cluster of nine CpGs." (PMID 34572100, 2021). "Recently, a region of chromosome 8q24.3, which includes plectin, has been identified as a risk locus for osteoarthritis." (PMID 34572100, 2021). "PLEC encodes Plectin a large cytoskeleton protein that is important in regulating cellular responses to mechanical stressors and is thought to play a role in the development of osteoarthritis but has not previously been associated with hip shape." (PMID 39574169, 2025).
Alzheimer disease (2 papers, 2022 to 2024). A progressive, neurodegenerative disease characterized by loss of function and death of nerve cells in several areas of the brain leading to loss of cognitive function such as memory and language. "Genes encoding the cytoskeleton-interacting proteins PLEC and PARVB are risk factors for Alzheimer’s disease, and genetic variants of PLEC and SYNE1 are high-risk alleles for bipolar disorder." (PMID 36400935, 2022).
bipolar disorder (2 papers, 2022 to 2024). A disorder of the brain that causes unusual shifts in mood, energy, activity levels and the ability to carry out day-to-day tasks. "Although DDR and apoptosis have already been described as risk factors for multiple sclerosis and bipolar disorder, the associated gene PLEC has not been described in the context of these diseases before." (PMID 39623312, 2024).
chronic pancreatitis (2 papers, 2021 to 2022). A chronic inflammatory process causing damage and fibrosis of the pancreatic parenchyma. "Plectin has also proved a distinguishing feature of PDAC compared to chronic pancreatitis (CP), which often has a similar clinical presentation." (PMID 34571895, 2021). "Recently, plectin was proposed to be a biomarker for CTCs of PDAC improving differentiation between malignant pancreatic disease and chronic pancreatitis." (PMID 35773413, 2022). "In comparison, 100% of the benign pancreas and chronic pancreatitis (CP) tissues were negative for plectin expression." (PMID 34571895, 2021).
colitis (2 papers, 2021 to 2023). Inflammation of the colon. "In conclusion, LXRs play an important role in regulating the function of the mouse colonic epithelium, and the inactivation of LXRαβ causes colitis similar to that seen in plectin knockout, but the direct regulator of the genes most changed in the LXRαβ−/− mouse colon was ERβ." (PMID 37569842, 2023). "To assess whether loss of plectin increases the susceptibility to colitis, we induced experimental colitis in Plefl/fl and PleΔIEC mice." (PMID 33674761, 2021). "Furthermore, we also demonstrate that loss of plectin can exacerbate experimental colitis in mice." (PMID 33674761, 2021). "We now confirm that LXRβ and LXRα are expressed in colonic epithelial cells and that as LXRαβ−/− mice age (above 12 months), there is dysfunction of the colonic epithelium and colitis, similar to that seen in plectin knockout mice." (PMID 37569842, 2023). "Plectin expression was reduced in the colons of ulcerative colitis patients and negatively correlated with the severity of colitis." (PMID 37569842, 2023). "In this study, we found that plectin expression was reduced in patients with active ulcerative colitis (UC) and that plectin expression levels negatively correlated with the severity of colitis." (PMID 33674761, 2021). "Moreover, plectin expression was reduced in the colons of ulcerative colitis (UC) patients and negatively correlated with the severity of colitis." (PMID 33674761, 2021). "The rapid deterioration of the PleΔIEC intestinal mucosa following weaning (i.e., a switch to a solid diet and the amplification of muscle contractions) indicates that the origin of colitis in the absence of plectin is primarily associated with a reduced capacity of IECs to resist mechanical stress." (PMID 33674761, 2021). "However, the possible regulation of ERβ on plectin, ELOVL1, and ChAT in colitis still needs more animal model experiments and clinical studies to investigate." (PMID 37569842, 2023). "We propose that the lack of functional plectin at HDs (in combination with its effects on KFs and Ds) and the resulting mechanical epithelial fragility favor an impaired intestinal barrier function and are ultimately responsible for colitis." (PMID 33674761, 2021). "Mice lacking plectin in an intestinal epithelial cell (IEC; PleΔIEC) spontaneously developed colitis characterized by extensive detachment of IECs from the basement membrane (BM), increased intestinal permeability, and inflammatory lesions." (PMID 33674761, 2021).
dilated cardiomyopathy (2 papers, 2016 to 2021). Cardiomyopathy which is characterized by dilation and contractile dysfunction of the left and right ventricles. "Three of these epitopes originate from plectin, a cytoskeletal protein that maintains tissue integrity and has been previously associated with myocarditis and dilated cardiomyopathy." (PMID 34956207, 2021).
head and neck squamous cell carcinoma (2 papers, 2016 to 2024). A squamous cell carcinoma that arises from any of the following anatomic sites: lip and oral cavity, nasal cavity, paranasal sinuses, pharynx, larynx, and salivary glands. "On the other hand, significantly increased expression of Plectin compared to non-cancerous tissues has been reported in invasive head and neck squamous cell carcinomas and that has been correlated with poor prognosis of the patients." (PMID 27470985, 2016).
heart failure (2 papers, 2013 to 2025). Inability of the heart to pump blood at an adequate rate to meet tissue metabolic requirements. "As the MCK promoter which drives the Cre-mediated knockout of plectin in skeletal muscle is also active in heart, the shorter life span of dKO mice could have been due to heart failure." (PMID 23758845, 2013).
metastatic disease (2 papers, 2015 to 2017). "Rikardsen and collaborators found high expression of plectin correlated significantly with disease-specific-survival in all patients with non-metastatic disease." (PMID 29088820, 2017). "The statistical analysis revealed that low expression of plectin in the tumor cells predicted a favorable outcome for patients with non-metastatic disease (p = 0.008)." (PMID 26306491, 2015). "The present study has shown that low expression of plectin predict a favorable outcome for patients with non-metastatic disease." (PMID 26306491, 2015). "However, in contrast to uPAR, high expression of plectin correlated significantly with DSD in all patients with non-metastatic disease, and not only the T1N0 subgroup." (PMID 26306491, 2015).
myofibrillar myopathies (2 papers, 2017 to 2021). "The most obvious manifestation of IF network integrity to be dependent on plectin is the spontaneous collapse and aggregation of desmin networks, observed in myofibers from plectin knockout (KO) mice and patients suffering from myofibrillar myopathies." (PMID 34440923, 2021).
Nail dystrophy (2 papers, 2021). Onychodystrophy (nail dystrophy) refers to nail changes apart from changes of the color (nail dyschromia) and involves partial or complete disruption of the various keratinous layers of the nail plate. "Besides EBS-MD, PLEC mutations lead to EBS with nail dystrophy, EBS-MD with a myasthenic syndrome, EBS with pyloric atresia, limb-girdle muscular dystrophy type R17, or EBS-Ogna." (PMID 34572129, 2021).
neuroblastoma (2 papers, 2020 to 2022). Neuroblastoma (NB) is the most common solid, extracranial childhood tumor. "PLEC, a cytoskeletal gene, contributed to the invasiveness of neuroblastoma and resistance to cisplatin." (PMID 35155430, 2022). "In addition to its predicted targeting of MYH9, miR-124-3p was predicted to target additional cytoskeletal genes (PLEC, ITGB1, VIM, and ACTN4) from our panel, which were overexpressed in the resistant SK-N-ASCis24 neuroblastoma cell model." (PMID 33330445, 2020). "These cytoskeletal genes (MYH9, PLEC, ITGB1) and mesenchymal markers (VIM, ACTN4), were previously reported by our lab to be up-regulated with cisplatin resistance development and involved in phenotypic and morphological modulation observed in our neuroblastoma cell model." (PMID 33330445, 2020). "The cytoskeletal genes MYH9, PLEC, ITGB1, VIM, and ACTN4, were previously reported by our lab to drive EMT-like morphological transformation and increased invasiveness (2.5 fold) in the MES SK-N-ASCis24 neuroblastoma cell line, coinciding with resistance development." (PMID 33330445, 2020).
non-small cell lung carcinoma (2 papers, 2022 to 2024). A group of at least three distinct histological types of lung cancer, including non-small cell squamous cell carcinoma, adenocarcinoma, and large cell carcinoma. "While on the other hand, PUF60 has been associated with colon and non-small cell lung cancer, and PLEC has been shown to promote the migration and invasion of neck squamous cell carcinoma." (PMID 35453681, 2022).
progressive muscular dystrophy (2 papers, 2015). "Most mutations in the human plectin gene (PLEC) cause autosomal recessive EBS-MD showing features of severe skin blistering and progressive muscular dystrophy." (PMID 25447312, 2015).
sarcoma (2 papers, 2021 to 2024). A usually aggressive malignant neoplasm of the soft tissue or bone. "Conversely, the low expression of plectin is considered an indicator of poorer overall survival in sarcoma, thymoma, pheochromocytoma, and paraganglioma, suggesting that the role of plectin in cancer may depend on tissue- or context-specific factors." (PMID 39334817, 2024).